USP17L20 (ubiquitin specific peptidase 17 like family member 20)
Description:
Deubiquitinating enzyme that removes conjugated ubiquitin from specific proteins to regulate different cellular processes that may include cell proliferation, progression through the cell cycle, apoptosis, cell migration, and the cellular response to viral infection.
Tractability: No criterion of Open Targets' tractability assessment is met for any kind of drug.
Gene: Protein-coding gene on chromosome 4 (9,258,124 to 9,259,716, forward strand). Ensembl gene ENSG00000250745.
Subcellular location: Nucleus; Endoplasmic reticulum
Pathways (Reactome):
Metabolism of proteins: Ub-specific processing proteases
Gene Ontology:
Molecular function: cysteine-type deubiquitinase activity
Biological process: regulation of apoptotic process; protein deubiquitination
Cellular component: endoplasmic reticulum; nucleus
Homologues: Paralogues in human: USP17L11 (99% identical), USP17L18 (99% identical), USP17L22 (99% identical), USP17L24 (99% identical), USP17L25 (99% identical), USP17L26 (99% identical), USP17L27 (99% identical), USP17L28 (99% identical), USP17L29 (99% identical), USP17L30 (99% identical), USP17L17 (99% identical), USP17L19 (99% identical), and 59 more.
Diseases named in the same sentence as USP17L20 in open-access papers:
USP17L20 is named in the same sentence as 1 disease in open-access papers, as found by Europe PMC text mining. Sharing a sentence is not in itself a finding about the gene and the disease. The quoted sentences say what the papers report.
ovarian carcinoma (1 paper, 2025). A malignant neoplasm originating from the surface ovarian epithelium. "In a similar study with the GeCKO library in the A2780 and SKOV3 ovarian cancer cell lines, ZNF587B, TADA1, SEMA4G, POTEC and USP17L20 were identified as candidate genes; among these, loss of ZNF587B and SULF1 gene expressions were associated with cisplatin resistance." (PMID 40242936, 2025).